PALD1 (phosphatase domain containing paladin 1)
Synonyms: KIAA1274; PALD
Tractability: PROTAC: ubiquitination databases record sites on it; its protein half-life has been measured.
Gene: Protein-coding gene on chromosome 10 (70,477,658 to 70,668,754, forward strand). Ensembl gene ENSG00000107719.
Subcellular location: Cytoplasm, cytosol
Subcellular location (Human Protein Atlas): Cytosol; Vesicles
Gene Ontology:
Molecular function: protein binding; protein tyrosine phosphatase activity
Cellular component: cytosol; cytoplasm; nucleus
Genetic constraint (gnomAD): Loss-of-function variants: 53 observed, 88.75 expected, observed/expected ratio (o/e) 0.6, 90% interval 0.48 to 0.75. The upper end of that interval is the gene's LOEUF score, 0.75, which puts it in group 3 of 6, group 1 being the genes least tolerant of losing a copy. Missense variants: 1,013 observed, 1,113.6 expected, observed/expected ratio (o/e) 0.91, 90% interval 0.86 to 0.96. Synonymous variants: 449 observed, 457.53 expected, observed/expected ratio (o/e) 0.98, 90% interval 0.91 to 1.06.
Homologues: Orthologues: chimpanzee PALD1 (99% identical), macaque PALD1 (96% identical), dog PALD1 (86% identical), pig PALD1 (86% identical), rat Pald1 (82% identical), guinea pig PALD1 (82% identical), mouse Pald1 (81% identical), rabbit PALD1 (79% identical), tropical clawed frog pald1 (62% identical), zebrafish pald1a (53% identical), zebrafish pald1b (52% identical). Paralogues in human: PTPDC1 (12% identical), CDC14A (10% identical), CDC14B (8% identical), CDC14C (7% identical), CDKN3 (4% identical), PTP4A1 (3% identical), PTP4A2 (3% identical), PTP4A3 (3% identical).
Diseases named in the same sentence as PALD1 in open-access papers:
PALD1 is named in the same sentence as 7 diseases in open-access papers, as found by Europe PMC text mining. Sharing a sentence is not in itself a finding about the gene and the disease. The quoted sentences say what the papers report.
emphysema (2 papers, 2017 to 2020). "Here we describe the phenotype of Pald1+/− and Pald1−/− mice and characterize lung defects linking Pald1 to sex-specific endothelial cell apoptosis, development of emphysema and COPD-like changes in females." (PMID 29133847, 2017). "Further studies are necessary to address how the lack of Pald1 leads to endothelial cell apoptosis and proliferation, and how that is related to the emphysema phenotype in a sex-specific manner." (PMID 29133847, 2017). "Here, we show that female, but not male, Pald1 heterozygous and homozygous knock-out mice display an emphysema-like histology with increased alveolar air spaces and impaired lung function with an obstructive phenotype." (PMID 29133847, 2017).
colon cancer (1 paper, 2022). "For the first time, we identify paladin, encoded by the PALD1 gene, as overexpressed in colon cancer." (PMID 35882839, 2022).
Obesity (1 paper, 2020). Accumulation of substantial excess body fat. "We found four strains with lower metabolic rate that might predict obesity susceptibility, Pax5+/-, Chst8-/-, Tfap2b+/-, and Pald1-/-." (PMID 32356724, 2020). "Strains with lower metabolic rate which might contribute to development of obesity include Chst8, Pax5, Pald1, and Tfap2b." (PMID 32356724, 2020).
type 2 diabetes (1 paper, 2025). "The DEG PALD1 is a negative regulator of insulin signaling in American Indians and is associated with type 2 diabetes in this population." (PMID 41465472, 2025).
cancer (1 paper, 2022). A tumor composed of atypical neoplastic, often pleomorphic cells that invade other tissues. "In this work, we explore the function of paladin, a protein encoded by the PALD1 (KIAA1274) gene, and that has never before been investigated in cancer." (PMID 35882839, 2022).
PALD1 also shares sentences with these, for which no sentence is quoted: Alzheimer disease (1 paper); lung disorder (1).